HOATZ (HOATZ cilia and flagella associated protein)
Description:
Required for motile ciliogenesis and flagellar genesis by mediating the maturation of the glycolytic enzyme ENO4.
Synonyms: C11orf88; FLJ46266
Tractability: No criterion of Open Targets' tractability assessment is met for any kind of drug.
Gene: Protein-coding gene on chromosome 11 (111,514,778 to 111,537,043, forward strand). Ensembl gene ENSG00000183644.
Subcellular location: Cytoplasm; Cell projection, cilium
Gene Ontology:
Biological process: axoneme assembly; cilium assembly; flagellated sperm motility; spermatogenesis
Cellular component: cilium; cytoplasm
Genetic constraint (gnomAD): Loss-of-function variants: 6 observed, 8.58 expected, observed/expected ratio (o/e) 0.7, 90% interval 0.38 to 1.37. That is too few expected variants to judge how well the gene tolerates losing a copy. Missense variants: 118 observed, 107.16 expected, observed/expected ratio (o/e) 1.1, 90% interval 0.95 to 1.28. Synonymous variants: 44 observed, 45.07 expected, observed/expected ratio (o/e) 0.98, 90% interval 0.77 to 1.25.
Homologues: Orthologues: chimpanzee HOATZ (99% identical), macaque HOATZ (95% identical), pig HOATZ (73% identical), dog HOATZ (70% identical), mouse Hoatz (70% identical), rat Hoatz (68% identical), rabbit HOATZ (66% identical), guinea pig HOATZ (65% identical). Paralogues in human: SELENON (20% identical), BEND2 (9% identical).